IGLV10-54 (immunoglobulin lambda variable 10-54)
Description:
V region of the variable domain of immunoglobulin light chains that participates in the antigen recognition. Immunoglobulins, also known as antibodies, are membrane-bound or secreted glycoproteins produced by B lymphocytes. In the recognition phase of humoral immunity, the membrane-bound immunoglobulins serve as receptors which, upon binding of a specific antigen, trigger the clonal expansion and differentiation of B lymphocytes into immunoglobulins-secreting plasma cells. Secreted immunoglobulins mediate the effector phase of humoral immunity, which results in the elimination of bound antigens. The antigen binding site is formed by the variable domain of one heavy chain, together with that of its associated light chain. Thus, each immunoglobulin has two antigen binding sites with remarkable affinity for a particular antigen. The variable domains are assembled by a process called V-(D)-J rearrangement and can then be subjected to somatic hypermutations which, after exposure to antigen and selection, allow affinity maturation for a particular antigen.
Synonyms: IGLV1054; V1-20
Gene: Immunoglobulin variable (V) gene on chromosome 22 (22,214,794 to 22,215,270, forward strand). Ensembl gene ENSG00000211642.
Subcellular location: Secreted; Cell membrane
Gene Ontology:
Biological process: immune response
Cellular component: extracellular region; immunoglobulin complex; plasma membrane
Homologues: Orthologues: macaque IGLV10-54 (82% identical), chimpanzee IGLV10-54 (81% identical). Paralogues in human: IGLV2-14 (60% identical), IGLV2-18 (59% identical), IGLV2-23 (56% identical), IGLV2-8 (56% identical), IGLV2-11 (56% identical), IGLV3-19 (55% identical), IGLV3-9 (54% identical), IGLV2-33 (52% identical), IGLV3-21 (52% identical), IGLV3-1 (51% identical), IGLV3-10 (51% identical), IGLV3-25 (50% identical), and 81 more.